EGFR (epidermal growth factor receptor)
Diseases named in the same sentence as EGFR in open-access papers (continued):
Sharing a sentence is not in itself a finding about the gene and the disease.
tumor (continued). "Compared to tumor cells co-injected with control tumor-supportive fibroblasts, tumor cells when co-injected with AREG-silenced fibroblasts showed a <2-fold reduction of activated, phospho-EGFR as measured by immunohistochemistry." (PMID 24068959, 2013). "Unfortunately, targeting angiogenesis or EGFR alone does not provide adequate tumor control in many patients." (PMID 23435217, 2013). "In this context, we showed that only a subset of EGFR-amplified tumor cells within GBM biopsies had a highly activated EGFR and importantly, these cells were found in non-angiogenic/invasive areas." (PMID 23429996, 2013). "In vivo studies reveal that immunoliposomes conjugated with different ligands to target specific tumor antigens, for example, VCAM-1, interleukin-13, and EGFR, may be of important clinical significance as a novel treatment for cancer." (PMID 24175095, 2013). "After the treatment with 100 and 200 mg/kg gefitinib, the expression level of Ki-67 in the tumor markedly decreased, whereas there was no significant change in the expression level of EGFR." (PMID 24191959, 2013). "Meanwhile, the expression of EGFR was elevated in all of the tumor compared to the mean in the respective non-neoplastic tissue." (PMID 24314030, 2013). "The tumor cells showed marked positivity for glial fibrillary acidic protein (GFAP) and S-100 proteins, whereas the cells were negative for epithelial membrane antigen (EMA), cytokeratins (CK) and epidermal growth factor receptor (EGFR)." (PMID 24137352, 2013). "In line with this idea, herein we showed that expression of CD43, in combination with oncogenic signals resulting from EGFR over-expression or from the expression of the HPV16 E6/E7 oncoproteins, promoted motility, anchorage-independent growth and in vivo tumor formation of murine fibroblasts." (PMID 24260485, 2013). "Quantification analysis of PET images showed much lower tumor as well as liver uptake at all time points (P < 0.05), suggesting successful blocking by the nonlabeled affibody and implying the high specificity of 64Cu-DOTA-ZEGFR:1907 for EGFR." (PMID 23710458, 2013). "In conclusion, we demonstrated that a subset of NSCLC EGFR-mutant patients did not experience tumor shrinkage, leading to unfavorable PFS and OS." (PMID 24376677, 2013). "In addition, andrographolide also decreased tumor formation by reducing VEGF, EGFR, Cyclin A, and Cyclin B expression on the transcriptional and translational levels." (PMID 23997793, 2013). "Other limitations of our study were that 3H-FLT was used instead of 18F-FLT and only one tumor model (A431) was used to compare the uptake of 3H-fluorothymidine with the uptake of 18F-FDG, Ki67 and phospho-EGFR after the treatment with two different doses of gefitinib." (PMID 24191959, 2013). "As EGFR promotes oncogenesis by activating the signaling pathways that regulate tumor formation and progression, it is not surprising that it has become one of the most heavily targeted molecules for therapy." (PMID 24349829, 2013). "Thus, a number of tumor cell lines triggers PBMC and MΦ to co-secrete an EGFR agonist and a STAT3 activator." (PMID 23597096, 2013). "Cetuximab is an epidermal growth factor receptor (EGFR) antagonist that decreases cellular proliferation and promotes apoptosis by hampering the pro-survival pathways fostered by EGFR overexpression in tumor cells." (PMID 23863691, 2013). "In EGFR (focal) amplified GBMs, the pattern of Chr7-tumor heterogeneity was found to be similar to that in GBMs without EGFR (focal) amplification." (PMID 24282558, 2013). "In this retrospective analysis of 30 PSCC patients with ≤ pN1 disease undergoing surgery without perioperative chemotherapy, tumor p-EGFR was the only significant prognostic factor on multivariable analysis." (PMID 23819610, 2013).
tumor (continued). "These common mutant EGFR proteins lead to constitutive activation of downstream extracellular signal-regulated kinase (ERK), phosphoinositide 3-kinase (PI3K)/Akt, and STAT signaling, resulting in ‘oncogene addiction’ and tumor cell growth and survival." (PMID 24189400, 2013). "Lapatinib but not other EGFR inhibitors synergized the anti-tumor activity of proteasome inhibitors both in vitro and in vivo." (PMID 24216290, 2013). "Most importantly, the in vivo data suggests that the dual inhibition of EGFR and Rictor produce significant inhibition of tumor growth, even in the absence of chemotherapy." (PMID 23555046, 2013). "The lack of pathways blockade in TCG2 model despite the EGFR dephosphorylation corroborates recent clinical data demonstrating that gefitinib has reached the tumor, efficiently dephosphorylated the target, but was not able to control the pathways activity." (PMID 23874590, 2013). "IgA2 EGFR did not have significant anti-tumour effect in WT mice; however it significantly inhibited tumour growth in FcαRI Tg mice at the end of the experiment compared to controls." (PMID 23918228, 2013). "In addition, it has been recently shown that EGFR signaling phosphorylates and enhances the activity of CK2, thereby promoting tumor cell invasion." (PMID 23669876, 2013). "Between Dec 4, 2006, and Aug 31, 2010, 1198 patients were enrolled, of whom 460 were included in the primary population of patients with KRASc.12–13,61 wild-type tumours and no previous EGFR targeted therapy." (PMID 23725851, 2013). "In the present study, we demonstrated that there were more tumor cell killing features in the COMB group than in the other groups and that the phosphorylation of EGFR was down-regulated, while the activation of caspase-3 was upregulated in the COMB group compared with that in the remaining groups." (PMID 23251234, 2013). "Using the morpholino-[124I]IPQA derivative, we obtained noninvasive microPET images of EGFR activity in L858R and E746-A750 del subcutaneous tumor xenografts, but not in subcutaneous tumor xenografts grown form control cell line." (PMID 23956990, 2013). "Moderate-to-high wtEGFR expression in a significant fraction (>10 %) of tumor cells (score ≥ 4) was detected in 77 (88.5 %) out of 87 EGFR-amplified tumors and in 26 (21.9 %) out of 119 non-amplified tumors." (PMID 23429996, 2013). "In tumor cells, activation of SSTR2 and ORs inhibit the phosphorylation of EGFR." (PMID 24059654, 2013). "According to our data, the median M/W ratio ranged from 0.13 to 18.15 in EGFR mutant cases and from 0.06 to 0.22 in wild-type cases, which suggests that cancer cells in bulk tumor tissue usually contain mutant and non-mutant types simultaneously." (PMID 23418425, 2013). "Although there is now widespread agreement that the presence of a KRAS mutation indicates that a patient is unlikely to respond to anti-EGFR therapy, there is some concern around the area of tumour heterogeneity." (PMID 23356214, 2013). "In effect, tumor cells with EGFR amplification no longer remained, or were dramatically reduced in serum monolayer." (PMID 24349039, 2013). "No, weak and strong EGFR expression was observed in 30 (50.0%), 16 (26.7) and 14 (23.3%) in tumor with Gleason scores < 7, respectively." (PMID 22546016, 2012). "Several signalling pathways seem to be important in hepatocarcinomas, and there is evidence that both EGFR-mediated mechanisms and the COX/prostaglandin system may be involved in the pathobiology of these tumours." (PMID 22967907, 2012). "In the current study, we found that the expression of EGFR and HER2 in vitro was correlated with the in vivo expression, which indicates that the expression of these tyrosine kinase receptors is largely an intrinsic feature of a tumor cell." (PMID 23046567, 2012).
tumor (continued). "We also examined cytoplasmic EGFR expression but it was not taken into consideration for further analysis because it was mainly weakly expressed in a low percentage of tumor cells (ranging from 2% to 10%)." (PMID 22475688, 2012). "The risk allele of rs3803662 was highly correlated with a subgroup of basal tumours that expresses EGFR and CK5/6 but not ER, PgR and ERBB2." (PMID 23270421, 2012). "A mutation in the BRAF oncogene occurs in approximately 10% of mCRC patients and is restricted to KRAS wild-type tumours, and was first shown to have a negative predictive value for anti-EGFR therapy." (PMID 22804917, 2012). "We conclude that autocrine EGFR signaling contributes to MDA-231 tumor growth in bone and the mammary gland independent of driving cancer cell proliferation." (PMID 22276166, 2012). "The HER family of tyrosine kinase receptors includes four members: HER1/epidermal growth factor receptor (EGFR), HER2, HER3 and HER4 that are expressed on tumor cell surfaces to mediate cellular growth and survival signals during interactions with their ligands in the tumor microenvironment." (PMID 22738135, 2012). "While these studies did not evaluate EGFR degradation, subsequent work in tumor cells with amplified cortactin gene levels indicates that cortactin upregulation prevents EGFR degradation, although the mechanism for this is unclear." (PMID 22952966, 2012). "Dimerisation of the human epidermal growth factor receptor (EGFR) protein family members, including HER1/EGFR and HER2, activates intracellular kinase and initiates a phosphorylation cascade that, in tumour cells, results in enhanced cellular proliferation and survival." (PMID 22240796, 2012). "OS was longer in patients with WT KRAS tumours who did not receive anti-EGFR therapy than in patients with MT KRAS tumours (26.9 months versus 20.2 months; HR: 1.48; 95% CI: 1.02–2.16; p = 0.0379)." (PMID 23174912, 2012). "Over all subsequent lines of therapy, 54 (24.7%) of the 219 patients with WT KRAS tumours had no subsequent therapy, 109 patients (49.8%) received anti-EGFR therapy, and 56 patients (25.6%) received no anti-EGFR therapy." (PMID 23174912, 2012). "Results were analyzed with respect to the clinical data, patient outcome, histological tumor type and presence or absence of EGFR gene amplification." (PMID 22159595, 2012). "SRM methodology provides a quantitative, sensitive, and reproducible approach for analysis of proteins in any biological sample and this report demonstrates the application of SRM methodology to measuring EGFR protein levels in FFPE biological samples, including patient tumor tissue." (PMID 22554165, 2012). "In order to mimic EGFR/Met crosstalk in the tumor microenvironment we used conditioned media from HGF-producing fibroblasts as well as co-cultures of TNBCs with these fibroblasts, and again demonstrated that the activation of Met mediated EGFR TKI resistance." (PMID 22788954, 2012). "Our data show for first time that ERβ1, by inducing these negative feedback pathways, is likely to exert a role of EGFR inhibitor and tumor suppressor function." (PMID 23158001, 2012). "These research studies suggest that EGFR expression, though correlating with tumor aggressiveness, does not necessarily predict response to anti-EGFR therapy." (PMID 23304129, 2012). "Overexpression of epidermal growth factor receptor (EGFR/ErbB1) has been reported in TNBC and may therefore be a valid target for anti-tumor therapy in TNBC." (PMID 22763464, 2012). "Similarly to MDA-MB-231, harvested primary mammary fat pad tumor tissue was immunohistochemically stained for CK18, EGFR and Her2 expression." (PMID 23118918, 2012). "It is likely that this pathway plays important roles in tumor progression, since elevated expression of ACK1 and cortactin due to gene amplification is found in several tumor types, and dysregulation of ACK1 and cortactin expression alters EGFR internalization dynamics." (PMID 22952966, 2012).
tumor (continued). "In addition, tumor xenografts from the NIH/3T3 HER2 and NIH/3T3 EGFR/HER2 cell lines had high levels of HER2, whereas HER2 homodimers were almost undetectable." (PMID 22829865, 2012). "In addition, comparison between EGFR FISH analysis and protein expression (determined as percentage of positive tumor cells, tH-score and cH-score) in CCRCC was assessed." (PMID 22475688, 2012). "Furthermore, the reduced RBM5 protein expression correlated with smoking status, tumor stage and lymph node metastasis of NSCLC, while overexpression of EGFR and KRAS proteins correlated with tumor stage and lymph node metastasis of NSCLC." (PMID 22537942, 2012). "Western blot analysis also revealed that in mice that were administered GSPs in diet the levels of EGFR and p-EGFR were decreased in tumor xenograft tissues compared with the tumor xenograft samples of those mice which were not given GSPs in diet." (PMID 23050025, 2012). "Whether normal gene dosage on especially chromosome 7 (containing EGFR, BRAF, cMET) is crucial for FTC-OV tumour survival is an important topic for future research." (PMID 22675538, 2012). "The differences in menstrual status, histology type, tumor stage and expression status of EGFR were not statistically significant." (PMID 23046633, 2012). "Pan-Alexa680(ON) detected the targeted tumor (MDA-MB-468, EGFR+); however, high background and non-specific tumor uptake (3T3/HER2) are evident on Day 1 through Day 3 post injection." (PMID 22510481, 2012). "For both alterations, the inhibitory ef fect is strong er for tumor cells than for cells with nor mal EGFR levels." (PMID 22399130, 2012). "Here, we demonstrate a requirement for MUC1 in carcinoma cell metastasis dependent on EGFR and Src without affecting primary tumor growth." (PMID 22586492, 2012). "Sixty-six tumors (96%) were classified as negative for EGFR staining, while only three (4%) showed EGFR positive staining in the tumor area." (PMID 23207070, 2012). "Moreover, in the tumor sections, the presence of the GLUT-1 and EGFR, as well as the expression of MMP-9 and Cathepsin B, was shown by immunohistochemistry as well as indicated by FLI." (PMID 22348134, 2012). "Here, we describe the development of antibody-based time-resolved Förster resonance energy transfer (TR-FRET) assays for the comprehensive analysis not only of EGFR and HER2 expression in tumor cryosections, but also of their activation through quantification of HER homo- or heterodimers." (PMID 22829865, 2012). "Therefore, we quantified the number of EGFR and HER2/cell in the cultured cell lines and assumed that the tumor xenografts derived from these cells had similar HER expression levels." (PMID 22829865, 2012). "No/intermediate or strong tumor labeling with EGFR Ext-Ab did not influence OS and PFS times whereas no/intermediate labeling with EGFR Int-Ab was associated with longer OS and PFS." (PMID 22159595, 2012). "In the BR.21 trial, patients with high polysomy/amplification were found to have a significantly higher RR than patients without these tumor qualities, and EGFR gene amplification was predictive of a survival benefit with erlotinib." (PMID 22992338, 2012). "In fact we observed a decrease of both phospho-EGFR and phospho-ErbB2 (not shown) in ErbB2 tumor cells upon treatment with AG1478." (PMID 23028720, 2012). "Although it is clear that the vast majority of patients with a K-ras mutant tumour will not respond to treatment, nearly 60% of patients will also not have a response to anti-EGFR antibody treatment despite having a K-ras WT tumour." (PMID 22666589, 2012). "The tyrosine kinase EGFR promotes via KRAS and PI3K mediated pathways tumor cell proliferation, cell survival and escape from apoptosis, while metabolic pathways are shifted towards synthesis of basic cellular elements such as nucleotids, fatty and amino acids." (PMID 23088930, 2012).
tumor (continued). "Correlation coefficients for pAkt-IR scores with pEGFR-IR, total EGFR-IR and PDFRß-IR scores in the tumour and non-malignant tissue samples." (PMID 23133535, 2012). "Of particular interest are peptide ligands for over-expressed receptors on tumor cells, such as the vascular endothelial growth factor receptor (VEGFR), somatostatin receptors and the epidermal growth factor receptor (EGFR), enzyme substrates and intracellular delivery sequences." (PMID 22929110, 2012). "Both these studies concluded that, because of the reversibility of binding to EGFR, these radiotracers were rapidly washed out of tumor tissue without generating an adequate target-to-background ratio." (PMID 22685650, 2012). "Of the clinical-pathological variables (age, size, LN, and tumor grade) and biomarkers (ER, PR, HER2, EGFR, TN status, VEGF-R1, and VEGF-R2) analyzed, tumor stromal VEGF-A expression levels were strongly correlated only with both epithelial and tumor stromal VEGF-R1 levels (P = 0.03 for both)." (PMID 22813402, 2012). "Tumour hypoxia, independent of VHL loss of function, increases EGFR expression through early growth response factor 1 (Egr-1)." (PMID 22937740, 2012). "More precisely, the cytoplasmic EGFR expression was found in 29/94 (30.8%) CCRCC tumors but ranged from 2% to 10% of positive tumor cells; therefore, it was not further commented." (PMID 22475688, 2012). "We also assessed slices from adjacent, colonic tissue close to the tumor, identified as EGFR negative in the same way previously performed for detection of CRC associated transcript-1 biomarker in malignant and pre-malignant CRC human tissues." (PMID 23144978, 2012). "Our data indicate that the expression of (p)EGFR and HER2 is largely an intrinsic feature of a tumor cell, while the in vivo expression of activated kinases of important cell signaling pathways can be substantially affected by the tumor microenvironment." (PMID 23046567, 2012). "This work summarises the multifaceted role of EGFR in the pathology of RCC, and it identifies EIPs that could help to provide mechanistic explanations for the different behaviours observed in tumours." (PMID 22937740, 2012). "Unexpectedly, the level of liver EGFR phosphorylation inhibition by AG1478 was not positively correlated with inhibition of tumor growth in the AOM model." (PMID 22761823, 2012). "Noted agents include a reversible 4-[(3,4-dichloro-6-[18F]fluorophenyl)amino]-6,7-dimethoxyquinazoline (ML01), which was tested in an EGFR overexpressing subcutaneous tumor." (PMID 22685650, 2012). "Furthermore, miR-7 regulates expression of other molecules downstream of EGFR in a coordinate fashion, including RAF1, IRS1, IRS2, PAK1, supporting a tumor suppressor function for miR-7 in these and other cancers." (PMID 23115635, 2012). "EGFR signaling activates a network of downstream pathways, including the phosphoinositide 3-kinase (PI3K)/Akt and Ras/Raf/ERK1/2 pathways, which promote tumor cell proliferation, invasion, metastasis, angiogenesis and apoptosis resistance." (PMID 23115635, 2012). "Compared with other anti-EGFR therapies the low toxicity and the lack of skin rash with Nimotuzumab is an advantage." (PMID 23342262, 2012). "Both EGFR and phosphor-EGFR were stained in the cell membranes although the degree of staining was not homogeneous within the tumor." (PMID 21554739, 2011). "The human epidermal growth factor receptor (EGFR) family of receptor tyrosine kinases, including EGFR, Her2, and Her3, is a potent target for antitumor strategies as it plays a critical role in HNSCC tumor cell growth, survival, invasion, metastasis and angiogenesis." (PMID 21801427, 2011). "In the remaining five patients (24%), there was not concordance in EGFR promoter methylation status between primary tumour and metastasis." (PMID 21559018, 2011).